INS (insulin)
Diseases named in the same sentence as INS in open-access papers (continued):
Sharing a sentence is not in itself a finding about the gene and the disease.
Hypoglycemia (continued). "In this population, HA is most often conceptualized as fear of hypoglycemia (FoH) comprised of specific worries associated with insulin reaction and the different behaviours to avoid hypoglycemia (see definition above) and measured with the Hypoglycemia Fear Survey." (PMID 32716932, 2020). "Second, the AA patients may require lower doses of oral hypoglycemic or even insulin treatment to avoid possible hypoglycemia associated with excessive insulin or OHA dosing." (PMID 32903749, 2020). "Despite its advantages in controlling glycemic dysregulation and preventing complications, insulin treatment may be associated with increased adverse cognitive outcomes possibly due to a greater risk of hypoglycemia." (PMID 30768625, 2019). "Insulin therapy is one of the most common causes of iatrogenic hypoglycemia." (PMID 30700277, 2019). "Advanced DKD patients progressing to dialysis may be susceptible to hypoglycemia due to decreased gluconeogenesis in the diseased kidneys, malnutrition due to uremia, altered oral hypoglycemic agents and insulin metabolism, and comorbidities." (PMID 30934740, 2019). "In addition, treat-to-target, randomized controlled trials (RCTs) have demonstrated that degludec is associated with a reduced risk of hypoglycemia compared with other basal insulin analogs, at equivalent glycemic control, for patients with either T1D or T2D." (PMID 31397845, 2019). "Subcutaneous insulin is associated with drastic decrease of blood glucose levels, whereas the oral administration of recombinant human insulin loaded with functionalized liposomes provided a more sustained hypoglycemia with less side effects." (PMID 31756981, 2019). "Therefore, even if basal insulin is suspended when hypoglycemia is detected, there is still some previously-injected insulin active in the plasma causing a lowering in BG concentration." (PMID 30922295, 2019). "Fear of hypoglycemia is associated with higher HbA1c levels and could be one of the reasons for higher personal glycemic targets with insulin therapy while coping with daily glycemic imbalance associated with PA." (PMID 31607950, 2019). "The beginning of treatment with insulin analogs at preconception, instead of at the beginning of pregnancy, may result in a smaller risk of severe hypoglycemia in women with DM1." (PMID 30786308, 2019). "Hence, this approach, taken for the first time here, potentially improves safety by better characterising SI potential variability for higher SI ranges, where the risk of experiencing hypoglycaemia due to insulin dosing is greater." (PMID 31640720, 2019). "A number of studies, as well as personal clinical experience, show that adaptation of the user’s insulin pump may be an important intervention to reduce the risk of hypoglycemia in the context of exercise." (PMID 31835538, 2019). "Oversecretion of insulin appears to have been the cause of the hypoglycemia in our patient." (PMID 31426870, 2019). "Hypoglycemia is a known risk factor for cardiovascular adverse events, and the use of insulin may be linked to an increase in life-threatening hypoglycemia events requiring external assistance for recovery." (PMID 31877127, 2019). "A mismatch between carbohydrate absorption and insulin action typically exists after large meals in individuals with T1D, particularly with large carbohydrate meals, leading to glucose fluctuations with excessive insulin increasing the risk of hypoglycaemia." (PMID 31067747, 2019). "Indeed, RAIAs induces a faster rise in plasma concentration, a higher peak concentration and a shorter subcutaneous residence time, which results in reduced PP glucose excursions and a lower risk of late hypoglycemia compared to regular human insulin." (PMID 31295897, 2019). "Although exercise may increase risk of hypoglycemia, only the individuals under insulin or insulin secretagogues (sulfonylureas and meglitinides) therapy seem to be at risk during, immediately after, or several hours after exercise." (PMID 31661946, 2019).
Hypoglycemia (continued). "The most immediate risk with intermittent fasting is the potential for hypoglycemia in patients who are on antidiabetic medications that are associated with hypoglycemia, specifically insulin (both prandial and basal) and sulfonylureas (including the short-acting meglitinides)." (PMID 31003482, 2019). "These suggest that appropriate patient selection with regular, supervised fine‐tuning of the basal insulin rate with intensive glucose monitoring might mitigate the residual hypoglycemia risk during Ramadan." (PMID 30938074, 2019). "Thus, the extract is increasing glucose sensitivity that leads into the increased insulin release and causes hypoglycemia." (PMID 31375555, 2019). "In addition, previous studies support the finding of this study that Chinese patients appear to be more concerned about the psychosocial aspects than the physical aspects (e.g., risk of hypoglycemia and weight gain) of insulin therapy." (PMID 30807441, 2019). "Depending on the risk of hypoglycemia as assessed by the practitioner, the testing could be as often as every two hours in the patient on insulin or every four hours on sulfonylureas." (PMID 31003482, 2019). "However, insulin therapy is associated with more frequent hypoglycemia, exposing patients to an array of autonomic and neuroglycopenic symptoms." (PMID 30886921, 2019). "Recent studies suggest that GLP-1 receptor agonists can replace rapid-acting insulin in basal insulin therapy, with cost-saving benefits, effective glycemic control, and reduced risk of weight gain and hypoglycemia in patients with T2D uncontrolled on conventional basal insulin regimen." (PMID 30901912, 2019). "Fetal RD could lead to continuous pancreatic β cell stimulation from the fetal stage through the neonatal period, causing insulin hypersecretion and neonatal hypoglycemia." (PMID 31019720, 2019). "This might suggest an increased risk of hypoglycemia with Empa when combined with SUs due to the known glucose-independent insulin-releasing effect of SUs." (PMID 31426529, 2019). "Inhaled insulin may be an advantage in poorly controlled diabetic patients who are averse to taking insulin injections, with faster onset of action and a shorter duration, thereby reducing risk of hypoglycemia." (PMID 31470605, 2019). "The SWITCH1 trial did not specifically study people at particular risk of severe nocturnal hypoglycaemia, which may be those with the greatest potential to benefit from insulin degludec." (PMID 31337371, 2019). "Most trials excluded patients with hypoglycemia unawareness or with a high risk of hypoglycemia, which in fact makes up the largest population group that could benefit from insulin analogues in the current clinical practice." (PMID 30622653, 2019). "This will include a discussion of the effectiveness as well as complications of renal replacement therapy, limiting the risk of hypoglycemia with judicious insulin and glucose administration, and the potential benefit and risks of hypertonic sodium bicarbonate." (PMID 30820692, 2019). "Use of antidiabetic agents, especially sulfonylurea (aHR = 1.31; 1.20–1.44; p < 0.001), glinide (aHR =1.20; 1.1–1.30; p < 0.001), and insulin (aHR = 2.63; 2.32–2.98; p < 0.001), predisposed patients to higher risks of severe hypoglycemia one year after dialysis." (PMID 30934740, 2019). "With respect to any age‐related differences in inclusion criteria relevant to the risk of hypoglycaemia, a larger proportion of older participants had been treated with insulin for more than 5 years (52.6% vs 47.6% of older and younger participants, respectively)." (PMID 30891886, 2019). "While these insulin therapies are efficacious in most patients, some additional therapies are warranted to support the control of blood glucose levels and reduce the risk of hypoglycemia in patients who respond poorly despite receiving appropriate treatment." (PMID 30781427, 2019).
Hypoglycemia (continued). "However, hyperglycemia is managed with trepidation in the neuro-intensive care unit (ICU) because of the risk of exacerbating CNS damage by induced hypoglycemia in the brain with insulin therapy." (PMID 30802174, 2019). "At the beginning of the treatment, the addition of a single injection of insulin is usually just as effective as using two injections, but with a lower risk of hypoglycemia and similar glycemic control is achievable as in the case of insulin delivery in multiple injections." (PMID 30871141, 2019). "In patients on a sulfonylurea or insulin (either alone or in combination with any other antidiabetic medication), the risk of hypoglycemia is significant, and the patient should be encouraged to do more frequent blood glucose testing, especially when first starting out with intermittent fasting." (PMID 31003482, 2019). "Insulin and sulfonylureas were associated with an increased risk of severe hypoglycemia." (PMID 31237921, 2019). "However, administration of exogenous insulin is difficult to tune and an excess of it can cause hypoglycemia (BG < 70 mg/dL), which leads to dizziness, lightheadedness, fainting, and, in the most extreme cases, coma or even death." (PMID 31323886, 2019). "Some papers have reported localized amyloidosis at the site of repeated insulin injection in a diabetic patient was the risk for hypoglycemia, it might be a reason of hypoglycemia in insulin users." (PMID 30815039, 2019). "Exogenous insulin treatment during fasting with changes in meal timing predisposes to hypoglycemia." (PMID 30938074, 2019). "As a venous route was often necessary, the continuous IV route seems preferable so as to facilitate restoration of water–electrolyte balance, avoid repeated SC injections, and reduce the risk of hypoglycemia, while ensuring better control of the insulin dose administered." (PMID 31418093, 2019). "This case highlights the need for patients on ivacaftor to be monitored extremely closely while concurrently on insulin as they may be at increased risk of hypoglycemia." (PMID 31010313, 2019). "However, people treated with insulin glargine showed a significant improvement in baseline to endpoint in HbA1c as compared to those people treated with NPH insulin at week 20 but with a lower risk of hypoglycemia." (PMID 31890395, 2019). "The risk of hypoglycemia with intermittent fasting while using insulin cannot be over emphasized and may even increase if the patient is successful in losing weight as a result of the intermittent fast." (PMID 31003482, 2019). "To test the safety of the insulin-loaded PAM-PAspPBA-b-PEG in mice, we determined that the injection of insulin-loaded PAM-PAspPBA-b-PEG did not cause death in the normal mice, whereas the injection of pure insulin at identical dosage caused the death of 50% mice due to hypoglycemia." (PMID 30423891, 2018). "Thus, several studies have shown a beneficial effect of glucagon in reducing the risk of hypoglycemia in insulin therapies." (PMID 29595915, 2018). "Regarding the small magnitude of the effect of long-acting insulin analogues in A1C, it is important to remember that its primary role in the algorithm for treating T1D is to improve glucose control and decrease the risk of hypoglycemia." (PMID 29649221, 2018). "Glucagon is a counter regulatory hormone and we hypothesize that a fixed ratio of insulin and a long‐acting glucagon‐analogue can reduce the risk of hypoglycemia." (PMID 29595915, 2018). "A battery of literature supports the effective and safe use of IDeg over other basal insulin analogs in T1DM adult population in terms of significant glycemic control with a lower risk of hypoglycemia, nocturnal hypoglycemia, dose requirement and higher flexibility." (PMID 30069184, 2018). "Although reducing insulin basal rate at exercise onset seems could help in attenuating the hypoglycemia risk, earlier timings might be needed for a better effect." (PMID 30713524, 2018).
Hypoglycemia (continued). "Our group has been exploring an alternative approach to boosting insulin signaling that obviates the risk of hypoglycemia: namely, pharmacological inhibition of insulin-degrading enzyme (IDE), the principal protease implicated in the catabolism and inactivation of insulin." (PMID 29447281, 2018). "In summary, these data support the hypothesis that a fixed ratio of insulin and a long‐acting glucagon‐analogue can reduce the risk of hypoglycemia." (PMID 29595915, 2018). "Compared to conventional multiple preprandial insulin regimens, injecting premixed fixed proportion of insulin before breakfast may increase the risk of hypoglycemia between meals, but this shortcoming can be solved using dividing one meal into two meals." (PMID 30285711, 2018). "Our goal was to find a fixed ratio of glucagon and insulin which could combine the ability to normalize blood glucose with reduced risk of hypoglycemia in diabetic rats." (PMID 29595915, 2018). "Hospitalized patients at risk of insulin-associated hypoglycemia can be identified using validated prediction models, which may support the development of real-time preventive interventions." (PMID 29527311, 2018). "A causal link between insulin-induced hypoglycemia and death was demonstrated by a case report that showed the presence of hypoglycemia, which was documented by continuous glucose monitoring data, at the time of the death of a young patient with type 1 diabetes." (PMID 30105256, 2018). "However, lifetime insulin administration has a high cost to patients, an elevated risk of hypoglycemia caused by improper insulin use, and can cause skin hypersensitivity reactions." (PMID 29725602, 2018). "Furthermore, GLP-1RAs in combination with basal insulin have been shown to reduce glycated Hb (HbA1c) and body weight, with a relatively low risk of hypoglycemia." (PMID 29688502, 2018). "Moreover, a pooled analysis from five RCTs revealed that addition of insulin glargine compared to NPH insulin to oral antidiabetic drugs in older adults was effective with low risk of hypoglycemia." (PMID 29527102, 2018). "Some studies suggest lower risk of neonatal hypoglycemia with use of metformin (an insulin sensitizing biguanide) in comparison to insulin therapy; however, due to increased metabolism in pregnancy, higher doses may be required." (PMID 30400566, 2018). "In clinical practice, BMI may indirectly mirror an individual’s insulin sensitivity and subsequent risk of hypoglycemia." (PMID 29473001, 2018). "Furthermore, without affecting the transcription of hepatic gluconeogenic enzymes, adrenalectomy causes exhaustion of hepatic glycogen and insulin-independent lethal hypoglycemia upon infection." (PMID 30375380, 2018). "Moreover, the proportion of participants using antidiabetic medication commonly implicated in iatrogenic hypoglycemia, such as insulin (26% vs. 32%, P = 0.31) or sulfonylurea (65% vs. 64%, P = 0.55), were also similar." (PMID 29473001, 2018). "However, a high risk of hypoglycaemia, reported in up to 1 of 3 hospitalized patients, has been associated with these multidose insulin regimens." (PMID 30208631, 2018). "Insulin and oral antihyperglycaemic agents, particularly those that increase insulin secretion independent of plasma glucose levels are the major causes for iatrogenic hypoglycaemia." (PMID 29884151, 2018). "Our data identify a GCK-dependent glucose-sensing mechanism during hypoglycemia that boosts responses to falling glucose; augmenting hypoglycemia-associated reduction in insulin secretion and the release of the counter-regulatory hormones glucagon and epinephrine." (PMID 30146176, 2018). "However, although insulin therapies decrease blood glucose, they are also associated with the risk of developing hypoglycemia." (PMID 29595915, 2018).
Hypoglycemia (continued). "These CGM-based findings have important implications for patient safety, as knowing the window of highest hypoglycemia risk for HIIE is different from that of aerobic exercise allows patients to adjust insulin dosage and carbohydrate intake accordingly for each type of activity." (PMID 30081478, 2018). "For example, an overdose of insulin could lead to hypoglycaemia while insufficient dose of the same medication could cause hyperglycaemic episode irrespective of the underlying effect of substance abuse." (PMID 30501025, 2018). "Increased insulin doses may lead to improved reductions in HbA1c levels (along with an increased risk of hypoglycaemia)." (PMID 29408938, 2018). "We demonstrated that SST cell ablation directly induced proportional changes in several types of hormone-producing endocrine cells within the islets and caused excessive insulin synthesis and release, which might contributed to the hypoglycemia." (PMID 29880854, 2018). "Shorter-acting secretagogues, the meglitinides (or glinides), also stimulate insulin release through similar mechanisms but may be associated with comparatively less hypoglycemia but they require more frequent dosing." (PMID 29527102, 2018). "Since all of the predictor variables are readily available in the EMR, our models could be used to develop a real-time informatics alert to prevent insulin-associated hypoglycemia in hospitalized patients, a potentially serious clinical outcome." (PMID 29527311, 2018). "Eventually, antibodybinding capacity is exceeded, and unbound free insulin causes hypoglycemia." (PMID 30462811, 2018). "Second, the fast-acting insulin available absorbs too slowly from subcutaneous tissue, has a delayed onset and has a too long glucose-lowering effect (up to 4–5 h), with an increased risk of late hypoglycaemia, in particular after a meal insulin bolus." (PMID 29954380, 2018). "A common contributor to hypoglycaemia is over-correction of high glucose values, which result from repeated injections of rapid-acting insulin within a short period of time causing overlapping or ‘stacking’ of insulin doses." (PMID 29423581, 2018). "On the other hand, in difficult-to-control patients, medications that increase the risk of hypoglycemia, including insulin, may be needed." (PMID 29713649, 2018). "Here we provide objective information on treatment modality (conventional insulin therapy, intensified insulin therapy, insulin pump), insulin dose and daily carbohydrate intake, glycaemic control and the risk of hypoglycaemia in CHI patients following pancreatic surgery." (PMID 30577875, 2018). "Studies of Type 2 diabetic patients showed different behaviour toward medication-taking than patients who were using insulin plus OHA, with different adherence being associated with education and instruction provided to insulin users, as well as fear of hypoglycaemia and injections." (PMID 30533042, 2018). "Certain patients are at higher risk for hypoglycemia and should receive lower insulin doses." (PMID 29688879, 2018). "Use of SMBG during exercise may also allow improved insulin management and reduce risk for hypoglycemia during and following exercise." (PMID 29527102, 2018). "Finally, compared to insulin analogues used in intermediate- or long-acting insulin preparations, NPH insulin is associated with peaks in exposure, which increases the risk of nocturnal hypoglycaemia when administered in the evening." (PMID 30116732, 2018). "Modern insulin analogues, with low risk of hypoglycemia and nocturnal hypoglycemia, may be used in such situations." (PMID 29460258, 2018). "These are known as automated closed-loop insulin delivery systems, also described as an artificial pancreas (AP), and their use has resulted in improved glucose control and reduced risk of nocturnal hypoglycemia in comparison with previous techniques." (PMID 32232085, 2018).